IL1B (interleukin 1 beta)
Diseases named in the same sentence as IL1B in open-access papers (continued):
Sharing a sentence is not in itself a finding about the gene and the disease.
fungal keratitis (13 papers, 2008 to 2025). "Transcriptome analysis of fungal keratitis revealed inflammatory cytokine genes, i.e., IL-1B, IL-6, TNF- α, to be significantly associated with fungal keratitis." (PMID 35328532, 2022). "Genes encoding IL-6 and IL-1β were expressed more than 300 fold during fungal keratitis." (PMID 18843377, 2008). "Former research in fungal keratitis indicated that inflammatory cytokines, IL-1β, IL-6, TNF- α, as well as Wnt, Hippo, and cGMP-PKG signaling pathways were significantly associated with the disease." (PMID 36838330, 2023). "At the advanced stages of fungal keratitis, the levels of IL-1β, IL-6, IL-8, and IFN-γ in the aqueous humor were shown to be significantly increased." (PMID 35328532, 2022). "In the current study, we investigated the expression of histone H3 (H3), acetylated histone H3 (AC-H3), HDAC1, TLR4, TNFα, and IL-1β in corneal specimens from patients with fungal keratitis and mice with experimental fungal keratitis." (PMID 31285488, 2019). "This was corroborated by results of real-time PCR at mRNA levels of TLR4, TNFα and IL-1β, as well as the ELISA results at protein levels of TNFα and IL-1β of the corneal specimens from mice with fungal keratitis." (PMID 31285488, 2019). "In our study, a high level of IL-1β was observed in the aqueous humor samples collected from fungal keratitis patients." (PMID 29673332, 2018). "The present studies demonstrate that a high concentration of IL-1β, IL-6, IL-8, and IFN-γ in the aqueous humor is associated with fungal keratitis, and the infiltrating PMN leukocytes are involved in this inflammatory response." (PMID 29673332, 2018). "At the advanced stages of fungal keratitis, the levels of IL-1β, IL-6, IL-8, and IFN-γ in the aqueous humor were significantly increased when compared with control (p<0.01)." (PMID 29673332, 2018). "High concentration of IL-1β, IL-6, IL-8, and IFN-γ in the aqueous humor was associated with fungal keratitis." (PMID 29673332, 2018). "Our experiment confirmed that Dectin-1 in early period of innate immune in rat fungal keratitis can work through IL-1β, IL-6, CCL2, CXCL1, CXCL2 to recruit neutrophils and macrophages to participate anti-fungal immunity." (PMID 26427623, 2015). "It was found that the expression of mRNA of TLR4, TNFα and IL-1β of the corneal specimens from mice with fungal keratitis was significantly suppressed after SAHA treatment compared with control, the production of TNFα and IL-1β was also inhibited with SAHA treatment as shown by ELISA assay." (PMID 31285488, 2019). "In the aqueous humor samples of fungal keratitis group, the levels of IL-1β, IL-6, IL-8, and IFN-γ were found to be significantly increased, as compared with the control group (P = 0.012 for IL-1β, P < 0.001 for IL-6, P < 0.001 for IL-8, and P = 0.001 for IFN-γ)." (PMID 29673332, 2018). "Dectin-1 in early period of innate immune responses in rat fungal keratitis might work through IL-1β, IL-6, CCL2, CXCL1, CXCL2 to recruit neutrophils and macrophages to participate anti-fungal immunity." (PMID 26427623, 2015). "Therefore, the increased IL-8, as observed in the aqueous humor of the fungal keratitis patients, could be a primary cause for the increased PMN infiltration and the high expression level of IL-1β." (PMID 29673332, 2018). "In this study, MMP9, along with other MMPs (MMP1, MMP7, MMP10, MMP12), pro-inflammatory cytokines (IL1B, TNF), and PRRs (TLR2, TLR4), were upregulated in bacterial and fungal keratitis." (PMID 35328532, 2022). "SAHA was able to inhibit experimental fungal keratitis in mouse by suppressing TLR4 and inflammatory cytokines such as TNFα and IL-1β; the inhibition of HDAC may be a potential therapeutic approach for the treatment of fungal keratitis." (PMID 31285488, 2019). "SAHA was able to inhibit experimental fungal keratitis by suppressing TLR4 and inflammatory cytokines (TNFα, IL-1β) and inhibition of HDAC may be a potential therapeutic approach for the treatment of fungal keratitis." (PMID 31285488, 2019).
fungal keratitis (continued). "IL-8 > IL-6 in patients with bacterial keratitis; IL-8 > IL-6 > IL-1β and increased frequency of circulating CD3−CD56+ NK cells in patients with gram-negative keratitis; and IL-8 = IL-6 > IL-1β in patients with fungal keratitis." (PMID 25741769, 2015). "Patients with fungal keratitis express IL-8, IL-6, and IL-1β in tears without changes in circulating cells." (PMID 25741769, 2015). "IL-1β measurements were as follows: 1135 ± 764 pg/mL in fungal keratitis; 423 ± 240 pg/mL in bacterial gram-negative keratitis, and 64 ± 40 pg/mL in bacterial gram-positive keratitis." (PMID 25741769, 2015). "Jeyalatha Mani et.al found that the expression of pro-inflammatory factors (IL-1β, IL-8, and IFN-γ) and TLRs (TLR-3/4/6) were significantly downregulated after CXL treatment in patients with fungal keratitis, suggesting that CXL may exerts an anti-inflammatory effect via TLRs pathway." (PMID 35836944, 2022).
Headache (13 papers, 2011 to 2026). Cephalgia, or pain sensed in various parts of the head, not confined to the area of distribution of any nerve. "Chemotherapy activates glial cells, such as microglia and astrocytes, which release pro-inflammatory cytokines, including IL-6, TNF-α, and IL-1β, sensitizing pain pathways and contributing to headache development." (PMID 41516139, 2025). "Several pro-inflammatory cytokines such as IL-6 and IL-1β are also nociceptive in the trigeminovascular system and take a part in the headache development." (PMID 37940864, 2023). "Another research reported findings of decreased IL-1β and elevated IL-6 levels during headache attacks and also demonstrated that IL-1β had the highest discriminative value between patients with headaches and controls compared to CRP and IL-6." (PMID 37176049, 2023). "In glyceryl trinitrate-induced experimental headache studies, activation of NFκβ, IL1β, IL-6 and NLRP3 inflammasome are shown within perivascular macrophages in the dura mater and in microglial cells nearby trigeminal sensory neurons in the brainstem." (PMID 34384355, 2021). "Their potential contribution to headaches was supported by data that application of IL-1β or TNFα on rat dura resulted in activation and sensitization of meningeal nociceptors." (PMID 34615455, 2021). "Although not fully understood, experimental data indicate that IL-1β promotes activation of trigemino-nociception and peripheral/central neuro-inflammatory pathways involved in headache onset." (PMID 30795781, 2019). "This cohort should include comprehensive biomarker collection, including serial measurements of inflammatory cytokines (IL-6, TNF-α, IL-1β), CGRP levels, markers of blood–brain barrier disruption, and genetic polymorphisms that may influence drug metabolism or headache susceptibility." (PMID 41516139, 2025). "Activation of resident mast cells in the meninges and release of proinflammatory cytokines such as IL-1β, IL-6, TNF-α and several chemokines have been proposed to play major roles in the progression of migraine headache." (PMID 34615455, 2021).
hearing loss (13 papers, 2009 to 2025). "We observed significant increases in nasal IL-1β and GM-CSF levels following noise exposure, particularly in participants with hearing loss." (PMID 40821651, 2025). "As anticipated, LPS induced Toll Like Receptor 4 (TLR4) signaling and augmented IL-1β expression and was associated with hearing loss." (PMID 19401759, 2009). "Elevated IL-1β and GM-CSF levels post-exposure correlate with hearing loss severity, suggesting that nasal cytokine measurements may be biomarkers for acoustic trauma risk." (PMID 40821651, 2025). "IL-1β, a pro-inflammatory cytokine, spiked immediately after shooting and remained elevated for 24 hours, while GM-CSF levels increased with the severity of hearing loss." (PMID 40821651, 2025). "Cochlear implantation could work as a rescue measure in cases of advanced, profound NLRP3-related hearing loss, and an anti-IL-1β agent could be beneficial for early diagnosed, mild hearing loss." (PMID 35812087, 2022). "Additionally, previous studies have demonstrated that increased ROS production and pro‐inflammatory cytokines, such as TNF‐α, IL‐1β, and IL‐6, play critical roles in cochlear tissue damage, in noise‐ or cisplatin‐induced hearing loss." (PMID 31353811, 2019). "We hypothesize that AIED patients who experience a break in tolerance and fail to express IL1R2 in response to antigenic stimuli, have unopposed IL-1β expression that leads to hearing loss." (PMID 19401759, 2009). "By promoting the release of cytokines such as IL-1β, IL-6, and TNF-α, and regulate the processes of programmed cell death, the NOD pathway can lead to hearing loss." (PMID 40353062, 2025). "In noise-induced hearing loss, the damage to fibrocytes of the spiral ligament is likely to lead to changes in cytokines or chemokines such as TNF-a, IL-1b, IL-6, and Icam-1." (PMID 34150778, 2021).
Hyperammonemia (13 papers, 2014 to 2026). An increased concentration of ammonia in the blood. "These steps could be targets to normalize neurotransmission in hyperammonemia and other pathologies associated with increased IL-1β by acting, for example, on p38 or PKCδ." (PMID 29422059, 2018). "The steps of the pathways identified could be targets to normalize neurotransmission in hyperammonemia and other pathologies associated with increased IL-1β by acting, for example, on p38 or PKCδ." (PMID 29422059, 2018). "Hyperammonemia increases (p < 0.01) the content of IL-1β to 244 ± 36 pg/mg protein compared to 126 ± 26 pg/mg protein in control rats." (PMID 36593485, 2023). "Concerning neurons, the increased transcription of IL-1β in hyperammonemia and MHE is due to increased nuclear translocation of NF-κB, which promotes transcription of IL-1β, TNFα and other pro-inflammatory factors." (PMID 36593485, 2023). "Hyperammonemia increased the IL-1β content in the hippocampus (139 ± 26%, p < 0.01), while blocking S1PR2 with JTE-013 completely reversed the increase in IL-1β (102 ± 17%; p < 0.05)." (PMID 38139078, 2023). "For example, hyperammonemia induces neuroinflammation in hippocampus, with activation of microglia and astrocytes and increased pro-inflammatory factors such as IL-1β and TNFα." (PMID 36593485, 2023). "Several studies confirmed that hyperammonemia activates the secretion of inflammatory cytokines (interleukin-6 (IL-6), interleukin-1beta (IL-1β), interferon gamma (IFN-γ), and tumor necrosis factor α (TNFα) in ammonia-induced astrocyte cultures." (PMID 35624703, 2022). "Increased membrane expression of TNFR1 in rats with chronic hyperammonemia leads to increased nuclear translocation of p50 subunit of NF-κB and, as a consequence, an increase of TNFα, IL1β, and glutaminase expression." (PMID 32917219, 2020). "Hyperammonemia increased the content of TNFα to 156 ± 8% (p < 0.01) and of IL1β to 132 ± 6% (p < 0.05) of control rats." (PMID 32917219, 2020). "It is shown that hyperammonemia increases IL-1β and activation of its receptor, leading to activation of Src which increases phosphorylation at Tyr1472 and membrane expression of GluN2B, which leads to activation of p38." (PMID 29422059, 2018). "The results reported show that hyperammonemia induces activation of astrocytes and microglia in the hippocampus, increasing the levels of pro-inflammatory cytokines IL-1β and IL-6." (PMID 26883214, 2016). "The results reported show that hyperammonemia induces astrocytes and microglia activation in the hippocampus, increasing pro-inflammatory cytokines IL-1β and IL-6." (PMID 26883214, 2016). "We hypothesize that hyperammonemia-induced increase in IL-1β in hippocampus would be responsible for the altered membrane expression of GluA1 and GluA2 subunits of AMPA receptors." (PMID 29422059, 2018). "We hypothesized that hyperammonemia-induced increase in IL-1β in hippocampus would be responsible for the altered GluA1 and GluA2 membrane expression." (PMID 29422059, 2018). "Hyperammonemia increases IL-1β, enhancing activation of IL-1 receptor." (PMID 29422059, 2018). "Hyperammonemia induces activation of microglia and of astrocytes which results in increased levels of Iba1, a marker of microglial activation, and of the pro-inflammatory IL-1b." (PMID 27090509, 2016). "We assessed if hyperammonemia increases the phosphorylation of p38 and the content of BDNF and if these effects are mediated by the S1PR2 → IL-1β → IL-1R → Src pathway." (PMID 38139078, 2023). "However, how hyperammonemia increases IL-1β in the hippocampus remains unclear." (PMID 38139078, 2023). "In rats with chronic hyperammonemia increased membrane expression of TNFR1 leads to increased nuclear translocation of NF-κB and, as a consequence, an increase of TNFα, IL1β, and glutaminase expression." (PMID 32917219, 2020).
Hyperammonemia (continued). "As it has been shown that IL-1β modulates membrane expression of AMPA receptors, we assessed its possible contribution to the effects of hyperammonemia." (PMID 29422059, 2018). "Hyperammonemia was similar before and after resolution of inflammation in patients.There was a significant decrease in the white blood cell count, nitrate/nitrite, IL-6, IL-1β, and TNF-α by infection treatment.Induced hyperammonemia significantly worsened neuropsychological test scores." (PMID 34361075, 2021). "Bicuculline treatment significantly reversed IL-1β expression in hyperammonemic rats (794 ± 41 cells/mm2, p < 0.001, compared with hyperammonemia without bicuculline), confirming the results obtained by Western blot." (PMID 34202516, 2021). "Bicuculline treatment did not alter the IL-1β content in control rats but significantly reversed the increase in hyperammonemic rats (97 ± 9% of controls, p < 0.01 compared with hyperammonemia without bicuculline) (F = 8.695), p < 0.0001)." (PMID 34202516, 2021). "However, IL-1β expression in hyperammonemic rats is increased in neurons of the CA1 region, not in astrocytes, in agreement with previous reports in rats with hyperammonemia and hepatic encephalopathy." (PMID 30858801, 2019). "We have also shown that both rats with hepatic encephalopathy and rats with hyperammonemia without liver failure show neuroinflammation, with increased levels of IL-1β and other pro-inflammatory markers, and altered membrane expression of AMPA receptor subunits GluA1 and GluA2 in hippocampus." (PMID 29422059, 2018).
hypothyroidism (13 papers, 2014 to 2025). Abnormally low levels of thyroid hormone. "Treatment with Kp10 suppressed the increase in NLRP3/Nlrp3, IL-1β, Il18, and Gasdermin D/Gsmd caused by hypothyroidism at the maternal-fetal interface." (PMID 37047793, 2023). "At the transcriptional level, expression of Klf9 decreased by 40.83%, while expression of Glut1, Pparg, and Il-1b increased due to hypothyroidism." (PMID 36143246, 2022). "Elevated serum levels of IL-1β are one of the main characteristic features of hypothyroidism." (PMID 40672362, 2025). "Immature mice exposed to IL-1β displayed a transient inflammation-induced hypothyroidism." (PMID 24240022, 2014). "For instance, the administration of T3 normalized the increased expression of the pro-inflammatory cytokines IL-1β, IL-6, and TNF-α in the hippocampus of rats with hypothyroidism." (PMID 39513900, 2024). "Inversely, IL1β levels were increased in WSB/EiJ mice (by 110% compared to their control group, p < 0.05), whereas IL10 levels were unaffected in response to hypothyroidism (p < 0.05)." (PMID 39409121, 2024). "Maternal hypothyroidism increased the gene and protein expressions of NLRP3, Caspase 1, IL-1β, and IL-18 in the deciduae and placentae of rats." (PMID 37047793, 2023).
Immunodeficiency (13 papers, 2016 to 2025). Failure of the immune system to protect the body adequately from infection, due to the absence or insufficiency of some component process or substance. "Individuals with ESRD have serious immune deficiencies and accumulate a large amount of uremic toxins, which stimulate the body to produce inflammatory factors such as TNF-α, IL-6, and IL-1β, leading to sustained microinflammation reaction." (PMID 37550622, 2023). "In addition, serum inflammatory cytokines IL-1β and IL-2 were increased in the model groups compared to that of the immunodeficiency group." (PMID 37317157, 2023). "Fibroblasts from patients multi-organ autoinflammation, immunodeficiency, and amylopectinosis due to loss of function mutations in RBCK1 and RNF31 exhibited diminished IL1B- and TNF-induced NFκB activation yet monocytes were hyper-responsive to IL1B." (PMID 32687504, 2020). "Murine TNF-α, IL-1β, and IL-6 in the negative control group (NSG mice without AAV-PCSK9 injection) were below the ELISA detection threshold (1–5 pg/mL), consistent with NSG mice's severe immunodeficiency, which limits murine immune responses." (PMID 40237461, 2025).